CDK5 (cyclin dependent kinase 5)
Diseases named in the same sentence as CDK5 in open-access papers (continued):
Sharing a sentence is not in itself a finding about the gene and the disease.
melanoma (15 papers, 2016 to 2025). A malignant, usually aggressive tumor composed of atypical, neoplastic melanocytes. "To ensure consistency between the observed phenotypes due to specific CDK5 inhibition and those observed from cells expressing the PP4R3β S840F variant identified in a melanoma patient, we replaced the endogenous CDK5 with a CDK5-AS variant in the malignant melanoma cell line A375." (PMID 31534152, 2019). "Activation of CDK5 leads to increased cell motility and invasion in melanoma cells both in vitro and in vivo." (PMID 37993880, 2023). "The in vivo studies carried out in melanoma-induced mice revealed down-regulation of Cdk5 and PD-L1, thereby resulting in about 79% decrease in the tumour growth and inhibition of lung metastasis." (PMID 36851335, 2023). "In a typical example, suppression of PD-L1 expression was attempted by knocking off of the cyclin-dependent kinase-5 (Cdk5) in melanoma cells through CRISPR-Cas9 delivered using the biodegradable cationic polymer poly(β-amino esters) (PBAE)." (PMID 36851335, 2023). "Knockout of endothelial Cdk5 reduced tumor growth of wildtype B16F1 melanoma cells, demonstrating that endothelial Cdk5 regulates tumor growth." (PMID 26755662, 2016). "In addition, CDK5 affects melanoma invasiveness and migration through regulation of the actin- and calmodulin-binding protein caldesmon." (PMID 37993880, 2023). "CDK5 and its activator p35 are highly expressed in human melanoma cells and tissues." (PMID 37993880, 2023). "CDK5 was found to regulate melanoma cell invasiveness by directly phosphorylating vimentin." (PMID 37993880, 2023). "Moreover, melanocyte-derived melanoblasts and adaptive resistant melanoma samples were characterized by different expression levels of certain transcription factors or genes involved in the CDK5 pathway." (PMID 30453548, 2018). "Additionally, knockdown of CDK5 in melanoma cell lines decreased cell motility and cell spreading in vitro, and decreased formation of lung and liver metastases in vivo in a mouse model of human melanoma." (PMID 28077789, 2017). "Abnormal expression of CDK5 or its activators (particularly p35) due to amplification, mRNA upregulation or their combinations has been found in several human cancers, including cancers of the colon, breast, lung, ovary, prostate and pancreas, as well as melanoma and hematological malignancies." (PMID 37993880, 2023). "Furthermore, CDK5 depletion inhibits lung and liver metastases in an in vivo melanoma model." (PMID 37993880, 2023). "In line with this, in melanoma, CDK5 could directly phosphorylate vimentin at Ser56." (PMID 33396266, 2020). "We also identified PHA-793887, a novel and potent inhibitor of CDK2, CDK5 and CDK723 as a compound that affects differentiation of melanoma cells." (PMID 32231230, 2020). "CDK5 has been found to affect the level of nuclear YAP and migration of melanoma cells." (PMID 39149855, 2024). "Pharmacological inhibition or shRNA-mediated knockdown of CDK5 inhibits invasion/migration, colony formation, and anchorage-independent growth of melanoma cells without affecting cell proliferation." (PMID 37993880, 2023). "In line, our study shows that Cdk5 inhibition alone inhibited B16F1 melanoma growth but not LLC tumor growth." (PMID 26755662, 2016).
Cerebral ischemia (14 papers, 2010 to 2024). Restriction of arterial blood supply to the brain associated with insufficient oxygenation to support the metabolic requirements of the tissue. "After brain ischemia, the rise in neuronal death is crucially associated by the Cdk5 hyper-activation mediated by p25." (PMID 24098701, 2013). "Our present finding strongly suggests that neuronal cell death after cerebral ischemia might be associated with Cdk5 activation." (PMID 31506563, 2019). "In addition to the many studies showing that CDK5 hyperactivation is involved in tau hyperphosphorylation and the subsequent development of dementia in neurodegenerative diseases, multiple pieces of evidence have implicated CDK5 in the progression of cerebral ischemia pathology." (PMID 25177270, 2014). "Inhibition of CDK5/p25 hyperactivity showed a neuroprotective effect in several brain ischemia models." (PMID 33429982, 2021). "After brain ischemia, CDK1 in vitro and CDK5 in vitro and in vivo are upregulated and associated with neuronal apoptosis." (PMID 33429982, 2021). "Using affinity assays, they observed that CDK5 was strongly associated with tau in the ischemic brain, suggesting a direct role of CDK5 on tau hyperphosphorylation after brain ischemia." (PMID 33429982, 2021). "It has been shown that Cdk5 activity is already intensified at 3 h after induction of brain ischemia." (PMID 34360858, 2021). "In cerebral ischemia models, pharmacological inhibition of CDK5 significantly reduces the infarct size after 24 h of reperfusion." (PMID 25177270, 2014). "Taken together, these findings indicate CDK5 as a pharmacologically accessible target for anti-angiogenic therapy and provide a basis for a new therapeutic strategy for cerebral ischemia." (PMID 25177270, 2014). "In conclusion, our results strongly support the idea that systemic administration of (S)-roscovitine reduces brain damage after cerebral ischemia in part through a CDK5 mechanism." (PMID 20711428, 2010). "CDK5 is involved in cognitive deterioration in cerebral ischemia and neurodegeneration." (PMID 25177270, 2014). "Interestingly, neuroprotective agents, such as atorvastatin, and CDK5 silencing after cerebral ischemia and in a glutamate-induced excitotoxicity model may act on the same cellular effectors to recover neurovascular unit integrity." (PMID 25177270, 2014). "In a large number of animal models of cerebral ischemia or neuronal cell ischemia models, Zincchelator, neuregulin-1 β, tfp5, and tat-Cdk5 CTM are found to have a neuroprotective effect through Cdk5 related pathways." (PMID 35966199, 2022).
glioma (13 papers, 2014 to 2024). A benign or malignant brain and spinal cord tumor that arises from glial cells (astrocytes, oligodendrocytes, ependymal cells). "Though further research is needed to understand mechanisms underlying Cdk5-mediated regulation of autophagy in glioma, our study definitely establishes this as a mechanism of RSV and TMZ + RSV mediated tumor growth inhibition." (PMID 30899038, 2019). "Larger studies are still desirable in the future to provide stronger evidence for CDK5 as a candidate diagnostic and prognostic biomarker of glioma." (PMID 26205145, 2015). "have documented a novel link between CDK5 and glioma CSCs, the mechanism underlying CDK5‐mediated TNBC stemness remains unclear and it is still unknown whether CDK5 blockade efficiently enhances immunotherapy in TNBC." (PMID 33240752, 2020). "Thus, our work proposes the combination of temozolomide and roscovitine as a novel potential therapeutic possibility in glioma and other cancers associated with Cdk5 overexpression." (PMID 30899038, 2019). "Further, our study found that CDK5 might be a significant diagnostic factor for glioma with a large population (n = 152) tested." (PMID 26205145, 2015). "Moreover, CDK5 expression has been linked to glioma aggressiveness." (PMID 39408617, 2024). "Higher CDK5 activity correlates with increased glioma cell growth and migration, which is further supported by evidence that the downregulation of CDK5 leads to reduced proliferation and induced apoptosis in glioma cells." (PMID 39408617, 2024). "5-HT6R has been found to induce Cdk5 activation in an agonist-independent manner in neuroblastoma and glioma cell lines." (PMID 39408617, 2024). "CDK5 also regulates glioma tumorigenicity by phosphorylating Tripartite motif containing 59 (TRIM59), a ubiquitin ligase." (PMID 37993880, 2023). "As deletion or mutation of the Nf1 gene, which encodes neurofibromin, is associated with poor prognosis in glioma, it underscores the role of CDK5 in promoting glioma via CRMP2." (PMID 37993880, 2023). "Multiple studies have shown that CDK5 increases proliferation and invasion in glioma cells and tumorigenesis in vivo." (PMID 37993880, 2023). "Increased p25 formation strongly correlated with enhanced apoptosis, indicating that while high CDK5/p35 promotes glioma tumorigenesis, intense CDK5 activity due to p25 formation results in cell death." (PMID 37993880, 2023). "Experiments were conducted to validate bioinformatics data reliability and the connection between CDK5 expression and clinicopathological features of gliomas." (PMID 34093802, 2021). "GSEA was conducted between the low and high CDK5 expression phenotype groups to identify the signaling pathways involved in glioma progression based on TCGA." (PMID 34093802, 2021). "Patients with glioma with higher CDK5 expression had a worse prognosis in TCGA cohorts {hazards ratio (HR) 1.02, 95% CI [1.01-1.03], P = 0.001}, which was validated in GSE16011 cohorts {hazards ratio (HR) 1.30, 95% CI [1.01-1.69], P = 0.043}." (PMID 34093802, 2021). "The CDK5 expression levels were significantly higher in the glioma cell lines than in the NHAs; therefore, U251MG cell line was selected for further analysis." (PMID 34093802, 2021). "By comparing tumor and normal tissues, we found that CDK5 mRNA levels were lower in glioma tissues than in normal tissues." (PMID 34093802, 2021). "EdU incorporation and colony forming assays showed that CDK5 promoted glioma cell proliferation and colony formation capacity." (PMID 34093802, 2021). "In our study, we assessed the influence of CDK5 on cell proliferation, apoptosis, and cell cycle of glioma cells by cell biological function assays." (PMID 34093802, 2021). "To investigate the predictive value of CDK5 in glioma prognosis, we analyzed CDK5 expression and the OS of glioma patients." (PMID 34093802, 2021). "All in all, we performed bioinformatics analysis to determine the prognostic value of CDK5 on gliomas." (PMID 34093802, 2021).
glioma (continued). "Although the role of CDK5 in gliomas has been previously investigated, relevant studies remain limited." (PMID 34093802, 2021). "In this study, we explored the prognostic value of CDK5 expression in patients with glioma based on The Cancer Genome Atlas (TCGA) and Gene Expression Omnibus (GEO) databases." (PMID 34093802, 2021). "More recently, the inhibition of CDK5 was reported to prevent glioma stem cell (GSC) self-renewal in vitro and in xenografted tumors." (PMID 32708903, 2020). "Based on these results, it appears that autophagy and Cdk5 activity are co-ordinately regulated by each other and Cdk5 has a complex role in autophagy regulation in glioma cells." (PMID 30899038, 2019). "Existing literature demonstrates that Cdk5 is highly up-regulated in gliomas when compared to normal human astrocytes." (PMID 30899038, 2019). "Another observation (previously unreported) in the current study is that direct knockdown of Cdk5 induces autophagy in glioma cell lines." (PMID 30899038, 2019). "We observed that TMZ treatment following a pre-treatment with RSV significantly enhanced chemo-sensitivity and suppressed the growth of glioma cells by reducing Cdk-5 activity and simultaneous induction of autophagy and Caspase-3 mediated apoptosis." (PMID 30899038, 2019). "In the current study, we observed that the increasing expression of CDK5 protein was significantly related to the pathological grade in our set of 152 glioma cases." (PMID 26205145, 2015). "CDK5-positive expression (57.2 %) was higher in glioma tissues than in normal brain tissues (12.5 %, Z = −3.400, P = 0.001)." (PMID 26205145, 2015). "The positive ratio of CDK5 in gliomas (57.2 %) was higher than that in normal brain tissues (12.5 %, P = 0.001)." (PMID 26205145, 2015). "Further, we continued to investigate the relationship between CDK5 expression and clinicopathological factors of gliomas, mainly the tumor grades." (PMID 26205145, 2015). "Spearman’s rank correlation confirmed that CDK5 was positively correlated with the pathological grade of glioma (r = 0.277, P = 0.001)." (PMID 26205145, 2015). "CDK5 expression level significantly contributed to diagnosing high-grade glioma (AUC = 0.666, 95 % CI 0.584, 0.749; P < 0.001)." (PMID 26205145, 2015). "Similar results were achieved in our current study that CDK5 expression was significantly upregulated in gliomas tissues, as compared to normal brain tissues." (PMID 26205145, 2015). "Immunohistochemical staining results showed that CDK5 protein was expressed in glioma cell cytoplasm." (PMID 26205145, 2015). "We firstly assessed by immunohistochemistry the expression of CDK5 in 152 glioma tissues and 16 normal brain tissues and further explored the relationship between CDK5 expression and other clinical features." (PMID 26205145, 2015). "The results disclosed a tendency of CDK5-positive ratio to increase in high-grade glioma compared to low-grade glioma (Z = −3.406, P = 0.001)." (PMID 26205145, 2015). "In this study, we aimed to evaluate the clinical value of CDK5 in different grades of glioma in relation to Ki-67 labeling index (LI)." (PMID 26205145, 2015). "Cdk5 activity can be modulated by its post-translational modifications, which may influence its role in glioma cell biology." (PMID 39408617, 2024). "CDK5 and p35 are overexpressed in gliomas compared to normal brain tissues." (PMID 37993880, 2023). "CDK5 in glioma cell lines (U251MG, U87MG, and U138MG) and NHAs was subjected to immunoblotting." (PMID 34093802, 2021). "Similar results were also obtained from GSE16011 dataset, indicating that CDK5 may be liable for glioma progression from a low-grade malignancy to an advanced malignancy." (PMID 34093802, 2021). "In vitro experiments were performed to explore the effects of CDK5 on glioma cell functions." (PMID 34093802, 2021). "Taken together, CDK5 might act as a potential prognostic biomarker and a tumor metabolism target for glioma." (PMID 34093802, 2021).
glioma (continued). "We further explored the role of CDK5 in human U251MG glioma cells via CDK5 knockdown." (PMID 34093802, 2021). "Next, we sought to elucidate the biological functions of CDK5 in glioma cells in vitro." (PMID 34093802, 2021). "Thus, similar to neuronal cells, there appears to be a direct autophagy inhibitory function of Cdk5 in glioma cells." (PMID 30899038, 2019). "More recent studies suggest that targeting CDK5 signaling to treat GBM could potentially eliminate CDK5-addicted glioma stem cells and reduce the likelihood of recurrence." (PMID 31842413, 2019). "We therefore investigated the possible role of Cdk5 in autophagy regulation in glioma cell lines." (PMID 30899038, 2019). "Thus, it was observed that Cdk5 expression is crucial to the survival of these glioma cell lines and down regulation of Cdk5 levels by specific SiRNA reduces the proliferation of U87 and U373 cells." (PMID 30899038, 2019). "Thus, we explored the effect of TMZ treatment on Cdk5 activity and autophagy in glioma cells in vitro." (PMID 30899038, 2019). "We showed that CDK5 regulates glioma tumorigenicity by promoting TRIM59 nuclear translocation via PIN1/importin α5 axis, leading to STAT3 signaling activation, and demonstrate that CDK5 mediates EGFR-stimulated STAT3 signaling through activation of the TRIM59/mH2A1 axis in GBM." (PMID 31488827, 2019). "Further, Cdk5 inhibition in glioma cells also leads to increased autophagy." (PMID 30899038, 2019). "Thus, the current study was to investigate the possible role of CDK5 in the tumorigenesis and aggressiveness of glioma and emphasized the relationship of CDK5 expression with Ki-67 labeling index (LI), which represents the status of tumor cell proliferation." (PMID 26205145, 2015). "The current result suggests that CDK5 may play an essential role in the tumorigenesis and aggressiveness of gliomas." (PMID 26205145, 2015). "Our results suggest that CDK5 may represent a valuable predictive marker of tumorigenesis and progression in glioma." (PMID 26205145, 2015). "Furthermore, Spearman’s rank correlation confirmed that CDK5 was positively correlated with the pathological grade of glioma (r = 0.831, P < 0.001)." (PMID 26205145, 2015). "In support of the previous studies, our result suggests that CDK5 may regulate multiple cellular processes and contribute to tumorigenesis by promoting tumor proliferation and deterioration in glioma." (PMID 26205145, 2015). "The most notable finding was that CDK5 could be a significant effect for diagnosing gliomas (AUC = 0.724, 95 % confidence interval (CI) 0.610, 0.837; P = 0.003)." (PMID 26205145, 2015). "However, previous studies on the role of CDK5 in glioma are still limited, and the clinical prognostic value of CDK5 remains unclear." (PMID 34093802, 2021). "Overall, CDK5 might prove to be a valid target for glioma therapy." (PMID 34093802, 2021). "Thus, it becomes exciting to hypothesize that Cdk5 inhibition may be a valid strategy to bypass the resistance to chemotherapy and radiation therapy in glioma." (PMID 30899038, 2019). "Moreover, it has been shown that CDK5 promotes the migration and invasion of glioma cells." (PMID 31842413, 2019). "Additionally, the strong correlation between CDK5 expression and Ki-67 LI was also found in our study, which disclosed that CDK5 could be involved in glioma cell proliferation." (PMID 26205145, 2015). "With further studies of CDK5, the researchers speculated the potential roles of CDK5 in glioma." (PMID 26205145, 2015). "The significant differences of CDK5 expression were also observed between WHO I glioma (34.8 %) and WHO III glioma (62.5 %), as well as WHO IV glioma (82.8 %; P = 0.026, P < 0.001, respectively)." (PMID 26205145, 2015). "Antagonizing CDK5 suppressed both self-renewal of GSC and glioma growth." (PMID 32708903, 2020).
glioma (continued). "Our data also demonstrates that reduced Cdk5 activity and altered downstream signaling may be one of the mechanisms mediating the cytotoxic effects of TMZ in glioma cells." (PMID 30899038, 2019). "Similarly, pharmacological CDK5 inhibition by roscovitine or genetic CDK5 down-regulation, by means of siRNA, abolished PTN-induced migration of human glioma U87MG cells." (PMID 29651006, 2018). "In the same line, PTN increases CDK5 activity and interaction with p35, in an RPTPβ/ζ-mediated manner, in rat glioma C6 cells that do not express ανβ32,4." (PMID 29651006, 2018). "Previous studies suggested that expression of cyclin-dependent kinase 5 (CDK5) may promote the migration and invasion of human glioma cells." (PMID 26205145, 2015). "However, there are no reports demonstrating the effects of Cdk5 knockdown in gliomas." (PMID 30899038, 2019). "In addition to inhibiting CDK7, SNS-032 also inhibits the cyclin-dependent kinases CDK2, CDK5 and CDK9, however, even though SNS-032 can alter glioma response to hypoxia, it is not toxic toward U87 cells even at very high drug concentrations (500 nM)." (PMID 29844863, 2018).